CLEC2A (C-type lectin domain family 2 member A)
Description:
Membrane-bound protein expressed mainly on keratinocytes which acts as a ligand to stimulate the activating receptor NKp65/KLRF2, expressed on the surface of natural killer (NK) cells. Facilitates thereby dedicated immune recognition of keratinocytes leading to natural killer cell mediated cytotoxicity. Also plays a role in modulating the extent of T-cell expansion.
Synonyms: KACL; PILAR; UNQ5792; INPE5792
Tractability: Antibody: UniProt places it where antibodies can reach, with high confidence; its Gene Ontology location is reachable by antibodies, with high confidence; UniProt predicts a signal peptide or a membrane-spanning region.
Gene: Protein-coding gene on chromosome 12 (9,898,673 to 9,932,370, reverse strand). Ensembl gene ENSG00000188393.
Subcellular location: Cell membrane
Subcellular location (Human Protein Atlas): Plasma membrane
Gene Ontology:
Molecular function: identical protein binding; protein binding; protein homodimerization activity; natural killer cell lectin-like receptor binding; receptor ligand activity
Biological process: natural killer cell mediated cytotoxicity; NK T cell activation; T cell receptor signaling pathway
Cellular component: external side of plasma membrane; plasma membrane
Genetic constraint (gnomAD): Loss-of-function variants: 5 observed, 10.1 expected, observed/expected ratio (o/e) 0.5, 90% interval 0.26 to 1.04. The upper end of that interval is the gene's LOEUF score, 1.04, which puts it in group 4 of 6, group 1 being the genes least tolerant of losing a copy. Missense variants: 121 observed, 141.81 expected, observed/expected ratio (o/e) 0.85, 90% interval 0.74 to 0.99. Synonymous variants: 50 observed, 43.61 expected, observed/expected ratio (o/e) 1.15, 90% interval 0.91 to 1.45.
Homologues: Orthologues: chimpanzee CLEC2A (99% identical), macaque CLEC2A (81% identical), zebrafish si:ch211-170d8.8 (22% identical), Drosophila melanogaster rgn (20% identical), zebrafish si:dkey-26c10.5 (19% identical), Caenorhabditis elegans clec-146 (16% identical), zebrafish si:ch211-193e13.5 (16% identical), Caenorhabditis elegans clec-196 (13% identical). Paralogues in human: CLEC2D (36% identical), CD69 (32% identical), CLEC2B (27% identical), CLEC2L (25% identical), CLEC12A (22% identical), KLRB1 (22% identical), KLRC1 (22% identical), CLEC1A (21% identical), KLRG1 (20% identical), KLRG2 (20% identical), CLEC12B (20% identical), KLRC3 (20% identical), and 11 more.
Diseases named in the same sentence as CLEC2A in open-access papers:
CLEC2A is named in the same sentence as 6 diseases in open-access papers, as found by Europe PMC text mining. Sharing a sentence is not in itself a finding about the gene and the disease. The quoted sentences say what the papers report.
xeroderma pigmentosum (2 papers, 2021 to 2025). Xeroderma pigmentosum (XP) is a rare genodermatosis characterized by extreme sensitivity to ultraviolet (UV)-induced changes in the skin and eyes, and multiple skin cancers. "Fibroblasts from both xeroderma pigmentosum patients and sporadic cSCC lose the receptor CLEC2A, which activates natural killer cells." (PMID 34553848, 2021). "In organotypic culture containing cSCC cell lines, normal fibroblasts, and natural killer cells, introduction of anti-CLEC2A antibody promotes invasion to the same extent as culture containing xeroderma pigmentosum fibroblasts." (PMID 34553848, 2021).
idiopathic intracranial hypertension (1 paper, 2024). "We found a significant difference between the two groups, in which genes such as CLEC2A, TBC1D3, and DPP10 were upregulated in the group of idiopathic intracranial hypertension." (PMID 39605979, 2024).
cancer (2 papers, 2022). A tumor composed of atypical neoplastic, often pleomorphic cells that invade other tissues. "The non-specific mAb clone 4C7 was used but likely detected here LLT1/CLEC2D and not CLEC2A/KACL, as the latter has not been reported to be expressed in these cancers." (PMID 35185935, 2022).
CLEC2A also shares sentences with these, for which no sentence is quoted: tumor (2 papers); inflammatory skin disease (1); squamous cell carcinoma (1).